SOX9 (SRY-box transcription factor 9)
Diseases named in the same sentence as SOX9 in open-access papers (continued):
Sharing a sentence is not in itself a finding about the gene and the disease.
colorectal cancer (continued). "Expressions of SOX9 in colorectal cancerous tissues and paracarcinoma tissues were detected by western blot, the results suggested that the expression of SOX9 in colorectal cancer tissues was significantly increased than that of adjacent tissues (P < 0.01)." (PMID 30285605, 2018). "By experimental verification, MALAT1 and SOX9 were expressed in a high percentage of colorectal cancer tumors and cells, while miR-145 was in a low expression." (PMID 30285605, 2018). "The regulatory function of lncRNA MALAT1 / miR-145 / SOX9 axis was revealed in colorectal cancer based on bioinformatics analysis." (PMID 30285605, 2018). "More importantly, SOX9 with up-regulated expression was indicated poor prognosis in colorectal cancer, glioma and lung cancer." (PMID 30285605, 2018). "Recent studies presented that uncontrolled expression of SOX9 was found in many kinds of cancers, such as glioma, lung cancer, colorectal cancer and so on." (PMID 30285605, 2018). "For the study, we determine the potential biomarkers and uncover the regulatory mechanisms of lncRNA MALAT1 / miR-145 / SOX9 axis on the abilities of cell growth and cell metastasis of colorectal cancer." (PMID 30285605, 2018). "In human intestine, HMGA1 and SOX9 are positively correlated, and both become upregulated in colorectal cancer." (PMID 28452345, 2017). "In human colorectal cancer cells it was shown that the transcription factor SOX9 binds to some cell cycle regulatory genes as a cofactor of NF-Y through the CCAAT motif." (PMID 27517874, 2016). "In this study, we show that SOX9 levels are higher in metastatic (SW620) than in primary colorectal cancer cells (SW480) derived from the same patient." (PMID 27571710, 2016). "Another study showed that SOX9 expression facilitated growth and proliferation of colorectal cancer cells, whereas inactivation reduced tumorigenicity." (PMID 26040697, 2015). "It has been reported that SHH signaling can maintain SOX9 overexpression in skin tumors and colorectal cancer." (PMID 26588701, 2015). "For example, SOX9 is upregulated in multiple malignancies, including prostate cancer, ovarian cancer, colorectal cancer, and hepatocellular carcinoma." (PMID 26384302, 2015). "Aberrant expression of SOX9 in many cancers, including colorectal cancer, suggests roles in these diseases as well and recent studies have suggested tissue- and context-specific roles of SOX9." (PMID 26040697, 2015). "Our finding of activation of proliferative genes through NF-Y, therefore, gives an insight into the oncogenic aspect of SOX9 and helps to explain why anti-oncogenic protein, SOX9 is highly expressed in some cancers including most colorectal cancer cells." (PMID 26040697, 2015). "The current study aimed to give insight into roles of SOX9 as a transcription factor by identifying SOX9 target genes in the genome of human colorectal cancer cells." (PMID 26040697, 2015). "Although, SOX9 has been reported to inhibit or sustain cell proliferation in different cell types, on the other hand, SOX9 is expressed in most human colorectal cancers as well as in human colorectal cancer cell lines." (PMID 26040697, 2015). "Additionally, we observed that the low-expression group exhibited a high mutational load, with FBXW7, SOX9, AMER1, SMAD4, ARID1A, and B2M being the most frequently mutated genes in colorectal cancer." (PMID 40170839, 2025). "Additionally, the activation of the SOX9/MMS22L-dependent DNA damage pathway promotes oxaliplatin resistance in colorectal cancer." (PMID 40240356, 2025). "Furthermore, inhibition of G9a in cholangiocarcinoma and colorectal cancer has been shown to reduce the levels of Sox9." (PMID 36896891, 2023).
colorectal cancer (continued). "In addition, claudin 7 expression is influenced by the activity of the WNT/TCF4 pathway in colonic epithelium and colorectal cancers in a manner that depends on the presence of transcription factor SOX9." (PMID 37998722, 2023). "Furthermore, the transcription factor SOX9 is overexpressed in colorectal carcinoma, suggesting that SOX9 is also involved in tumorigenesis." (PMID 36986600, 2023). "Mechanistically, SOX9 is targeted by miR-487a-3p in colorectal cancer cells." (PMID 35444536, 2022). "Additionally, colorectal cancer cells displayed low miR-487a-3p levels, promoting SOX9 expression in colorectal HT29 and SW480 cells, exhibiting the DDP-resistant phenotype." (PMID 35444536, 2022). "Finally, the levels of expression of RIP140 and SOX9 exhibit a reverse response and prognosis value in human colorectal cancer biopsies." (PMID 34206767, 2021). "SRY-box transcription factor 9 (SOX9), as a chemoradiotherapy-sensitive gene in colorectal cancer patients, could be a suitable biomarker to predict the relapse after the treatment." (PMID 33520987, 2020). "Digital image analysis (DIA) of multiplex fluorescence-based immunohistochemistry and visual chromogenic evaluation of CDX2, SOX2, SOX9, E-cadherin, and β-catenin in colorectal cancer are comparable, recognizing prognostic value of CDX2 and negative correlation with SOX2." (PMID 31641225, 2020). "In this study, we hypothesized that SOX9 could regulate the function of cancer stem/initiating cells (CSCs) to further facilitate the progression of colorectal cancer (CRC)." (PMID 33318478, 2020). "On the other hand, SOX9 might have a dose-dependent effect, which has already been suggested for colorectal cancer, where the same apparently contradictory observations have been reported." (PMID 31275454, 2019). "Likewise, overexpression of NEDD9 suggests poor prognosis in patients with colorectal cancer and promotes migration and progression of colon cancer cells through Wnt signaling, while SOX9 is known to mediate NEDD9 in melanomas." (PMID 31671847, 2019). "Therefore, MALAT1, miR-145 and SOX9 are indicated to be novel promising candidates for developing effective therapeutic strategies for colorectal cancer." (PMID 30285605, 2018). "Moreover, over-expression of MALAT1 enhanced the cell growth of colorectal cancer cells, whereas miR-145 showed the opposite effect through repressing SOX9 expression." (PMID 30285605, 2018). "We speculate that this inconsistency may result from the insufficient number of cases or that SOX9 may have a special role in colorectal cancer." (PMID 30285605, 2018). "Similarly, in the two groups of cell lines in the colony formation assay, the clone number of colorectal cancer cells with the knockdown of SOX9 was significantly smaller than that of the NC group." (PMID 30285605, 2018). "We might draw the conclusion that down-regulation of SOX9 promoted cell apoptosis and induced G1 cell cycle arrest of colorectal cancer." (PMID 30285605, 2018). "Among the differential lncRNAs and genes which could establish lncRNA-miRNA-mRNA regulatory axis, MALAT1 and SOX9 were found to be close to colorectal cancer progress through references." (PMID 30285605, 2018). "Because HMGA1 is overexpressed in diverse epithelial cancers and correlates with cancer stem cell properties in experimental models, we also sought to determine whether HMGA1 and SOX9 are co-regulated in colorectal cancer." (PMID 28452345, 2017). "In addition, SOX9 expression is an important biomarker for the prediction of colorectal cancer relapse." (PMID 28061475, 2017). "Moreover, both HMGA1 and SOX9 are positively correlated in human intestinal epithelium, and both become markedly upregulated in colorectal cancer." (PMID 28452345, 2017). "SOX9 was already reported to act on B-Catenin and PPARRgamma activation in colorectal cancer." (PMID 28002797, 2017).
colorectal cancer (continued). "Moreover, overexpression and knockdown of SOX9 were performed through an overexpression plasmid in the human colorectal carcinoma cell lines Caco-2 and DLD-1 and through siRNA in HCT116 and HT-29 cells, respectively." (PMID 28279198, 2017). "SOX9 is overexpressed in both colorectal cancer and hormone-refractory prostate cancer and has been correlated with poor patient survival in colorectal cancer and enhanced in vivo tumor growth, angiogenesis, and invasion in a LNCaP prostate cancer xenograft model." (PMID 27600078, 2016). "Furthermore, strong SOX9 expression is an independent indicator for an adverse prognosis in colorectal cancer." (PMID 27649156, 2016). "To test whether SOX9 and NF-Y interact in the nuclei of colorectal cancer cells, we performed in situ PLA on HT29 and HCT116 cells." (PMID 26040697, 2015). "To gain insight into SOX9-mediated transcriptional regulation in colorectal cancer cells, we first attempted to identify its physiological targets on a genome-scale using chromatin immunoprecipitation (ChIP) followed by sequencing (ChIP-seq) in human colorectal cancer cells." (PMID 26040697, 2015). "We hypothesize that dimerization of SOX9 is likely also required for transactivation of some genes in colorectal cancer cells." (PMID 26040697, 2015). "Aberrant expression of SOX9 in some human cancers, including colorectal cancer and in Apc(min/+) mouse intestinal adenomas suggest roles of SOX9 in colorectal cancer and to delineate the roles of SOX9 in colorectal cancer has been a focus of some recent studies." (PMID 26040697, 2015). "To confirm whether SOX9 also binds to DNA through this motif in colorectal cancer cells, we used the motif discovery tool MEME." (PMID 26040697, 2015). "However, there has not been a report of genome-wide ChIP analysis in intestinal or there have been few reports identifying SOX9 targets in intestinal epithelium or colorectal cancer cells." (PMID 26040697, 2015). "The current study revealed that, in colorectal cancer cells, SOX9 is recruited by NF-Y to the target genes and interacts with NF-Y on CCAAT promoter sequences and that SOX9 is necessary for the function of NF-Y in activating expression of some cell-cycle regulatory gene expressions." (PMID 26040697, 2015). "It is in consistent with our latest immunostaining results (unpublished data), indicating that SOX9 may play oncogenic roles and serve as an independent adverse prognosticator in colorectal cancers." (PMID 16504081, 2006). "Particularly, SOX9 was upregulated in most colorectal cancers." (PMID 16504081, 2006). "SOX9 may thus be a potential target gene for prognostic assessment and therapeutic intervention in colorectal cancers." (PMID 16504081, 2006). "Besides, SOX9 expression levels are related with chemoresistance in gastric, pancreatic, and colorectal cancer and high expression of SOX9 in several solid tumors is related to poor overall survival, biochemical recurrence-free survival, disease-specific survival, and DFS." (PMID 31057614, 2019). "Thus, there are multiple distinct mechanisms that could give rise to overexpression of HMGA1 and SOX9 in colorectal cancer, and SOX9 may depend, at least in part, on genetic lesions distinct from HMGA1 overexpression in this setting." (PMID 28452345, 2017). "The extent to which the developmental transcription factor SOX9 functions as an oncogene or tumor suppressor in colorectal carcinoma (CRC) is debatable." (PMID 27248473, 2016). "Our results are also in accordance with a study performed in colorectal cancer reporting that loss of SOX9 expression in the invasive front of the tumours predicts tumour relapse in stage II colon cancer patients, although the prognostic value of SOX9 is also not consensual in colorectal cancer." (PMID 31275454, 2019).
colorectal cancer (continued). "Taken together, to make an investigation on the critical function and mechanism of MALAT1/miR-145/SOX9 in colorectal cancer, the expression and the correlation among MALAT1, miR-145 and SOX9 were determined." (PMID 30285605, 2018). "Our data obtained using human colorectal cancer cells show that some cell cycle regulatory genes exhibit enriched SOX9 binding to the CCAAT motif, and that those SOX9 enriched sites overlap precisely with NF-Y binding peaks in the proximal promoters." (PMID 26040697, 2015). "Moreover, SOX9, which is activated by FARSA-AS1, promotes the growth, stemness, and metastasis of colorectal cancer." (PMID 38164286, 2024). "TTP has been shown to directly regulate EMT regulators, including ZEB1 (zinc finger E-box binding homeobox 1), SOX9 (sex-determining region Y box 9), and MACC1 (metastasis associated in colon cancer 1), all of which are known to be downregulated in colorectal carcinomas (CRC)." (PMID 32545247, 2020). "Strikingly, both HMGA1 and SOX9 are markedly upregulated in human colorectal cancer (P<0.0000001), although their expression was not correlated in this setting." (PMID 28452345, 2017). "Although HMGA1 and SOX9 are positively correlated in normal colonic epithelium and both become upregulated in cancer, it is not surprising that the correlation is lost in colorectal cancer." (PMID 28452345, 2017). "Among the up-regulated genes in colorectal cancer, we found 14 genes involved in signal transduction (TDGF1 and ENC1), transcription (SOX9, MYC, and HGFR/MET), nuclear transport (NUP62, NUPL1, NUP155, KPNA2, RANBP5, CSE1L/CAS, NTF2, and RANBP1) and cellular transport (SLCO4A1)." (PMID 16919171, 2006). "We could see that in si-MALAT1 group, the expression of miR-145 was higher and SOX9 was lower than NC group, further verifying the knockdown of MALAT1 inhibited the growth of colorectal cancer in vivo by up-regulating miR-145 and down-regulating SOX9 (P < 0.01)." (PMID 30285605, 2018). "The OD value of si-SOX9 + miR-145 inhibitor group showed no significant change compared with the NC group, suggesting that the down-regulation of SOX9 inhibited the proliferation of colorectal cancer cells (P < 0.01)." (PMID 30285605, 2018). "For example, SOX9 transcriptionally activated FOXK2, which belongs to the fork head DNA binding protein family, has been shown to play a critical role in tumorigenesis, high expression of FOXK2 is significantly correlated with poor survival of colorectal cancer." (PMID 29348895, 2017). "In light of this report, an interesting future direction is to reveal whether or not SOX9 may also play a role by binding with NF-Y to its non-traditional, cell type-specific enhancers in colorectal cancer cells." (PMID 26040697, 2015). "In colorectal cancer cells, WNT/TCF4 activation in the absence of SOX9 leads to high claudin 7 expression, which has diffuse localization in the basolateral membrane and favors loss of polarity." (PMID 37998722, 2023). "In addition, MG cells expressed surface markers of colorectal cancer stem cells (ALDH1A1, CD24, POU5F1, SOX2, and SOX9) to a greater degree compared with non-MG cells." (PMID 31936744, 2020). "Sox9 signaling showed to be essential in the EMT mechanism in non-small-cell lung carcinoma cell, mouse embryonic mammary cells, mouse gastric cancer cells, human colorectal cancer cells, human hepatocellular carcinoma cells, thyroid cancer cells, and avian neural crest cells in vitro." (PMID 32974338, 2020).
melanoma (76 papers, 2011 to 2025). A malignant, usually aggressive tumor composed of atypical, neoplastic melanocytes. "In contrast, SOX9 is associated with neural crest specification and when upregulated in melanoma, has been shown to induce a more differentiated and less proliferative phenotype, including cell cycle arrest via p21." (PMID 41465475, 2025). "NR2F1 overexpression is reported to upregulate SOX9 through RAR-β; SOX9 overexpression has been linked to the promotion of migration, metastasis, and resistance to targeted therapy in melanoma." (PMID 40955663, 2025). "Ectopic WT-Bmal1 and dHLH-Bmal1 increased genes associated with mesenchymal melanoma state, such as Sox9, Fn1, Col1a1, Prrx2, Klf4, Snai2, Twist2, Lmo1 and Axl31." (PMID 38245503, 2024). "Supporting the results from the melanoma cell lines, we found increased expression of SOX9 and loss of expression of SOX2, SOX5, and SOX8, suggesting that SOX10KO cells reverted to a pre-NC state." (PMID 36040798, 2022). "For example, X chromosome linked, sex-determining region Y box 9 (SOX9) transcriptionally regulates CEACAM1 expression in melanoma cells and thereby their immune resistance." (PMID 32226299, 2020). "We then examined the impact of SOX9 OE on a panel of matrix metalloproteinases (MMPs) expression which has been implicated in promoting melanoma metastasis through proteolysis of extracellular matrix." (PMID 30642390, 2019). "In melanoma, previous works demonstrated that overexpression of SOX9 inhibits growth of melanoma cells and causes cell cycle arrest." (PMID 26885752, 2016). "Here we show in several melanoma cell lines that overexpression or knockdown of SOX9 causes down-regulation or up-regulation of CEACAM1, respectively, in mRNA and protein levels." (PMID 26885752, 2016). "The suppressive effect of SOX9 on the promoter was significantly hindered in the construct bearing the mutated Sp1 binding site, in all three melanoma lines." (PMID 26885752, 2016). "Notably, Hif1α or Sox9 expression in melanoma is associated with tumorigenesis, suggesting their putative roles in Bmal1-dependent B16-F10 tumorigenesis." (PMID 38245503, 2024). "Indeed, SOX10 positive melanoma cells show an upregulation of genes implicated in pigmentation and cell differentiation while SOX9 positive melanoma cells show an upregulation of genes implicated in EMT." (PMID 35406721, 2022). "On the other hand, previous studies showed that either overexpression of SOX9 alone or upregulation of SOX9 expression in SOX10 KD caused cell cycle arrest through an increase in cyclin-dependent kinase inhibitor p21 protein expression in melanoma cell lines." (PMID 30642390, 2019). "Downstream consequences of such confounding factors were exemplified in a recent publication, in which the authors inferred a coessentiality network using the Achilles dataset and reported that SOX9 is part of a gene cluster highly specific to BRAF-mutated melanoma cell lines." (PMID 30683138, 2019). "Furthermore, our immunohistochemistry showed the detection of SOX9 mRNA and protein exclusively in the metastatic melanomas, that is in accord with a previous study in which high SOX9 is associated with lower survival rates of patients with advanced melanoma." (PMID 30642390, 2019). "In addition, SOX9 promotes malignant properties of melanoma and glioblastoma cell lines and is associated with lower rates of survival for both cancers." (PMID 27880766, 2016). "Based on our findings it is conceivable that increased levels of SOX9 might mediate at least some of the anti-tumorigenic effects observed upon SOX10 loss-of-function in melanoma." (PMID 25629959, 2015). "Given the importance of cofactors in conferring tissue-specific action of SOX9, it is conceivable that distinct SOX9 expression levels may associate with different cofactors to orchestrate differential regulation of target genes and the subsequent impact on melanoma growth and invasion." (PMID 30642390, 2019).